CSF3 (colony stimulating factor 3)
Diseases named in the same sentence as CSF3 in open-access papers (continued):
Sharing a sentence is not in itself a finding about the gene and the disease.
thymoma (3 papers, 2023 to 2025). A neoplasm arising from the epithelial cells of the thymus. "PDCD1 expression was similarly greatly raised in thymoma, whereas CSF3 expression was significantly reduced." (PMID 37644514, 2023). "We found that PDCD1 expression was enhanced in the thymoma, but CSF3 expression decreased." (PMID 37644514, 2023). "We evaluated the effect of PDCD1 and CSF3 on thymoma immune infiltration patterns." (PMID 37644514, 2023). "Using the TCGA dataset, we focused on the expression pattern of PDCD1 and CSF3 in thymoma tissue." (PMID 37644514, 2023). "The immune infiltration analysis of aberrant PDCD1 and CSF3 expression revealed that T cells, including Th2 cells, CD8 + T cells, and Th17 cells, were highly enriched and activated within the thymoma." (PMID 37644514, 2023).
acute monocytic leukemia (2 papers, 2015 to 2017). Acute monoblastic leukemia (AML-M5), is one of the most common subtypes of acute myeloid leukemia (AML) that is either comprised of more than 80% of monoblasts (AML-M5a) or 30-80% monoblasts with (pro)monocytic differentiation (AML-M5b). "Third, the production of CSF3, IL-1β, and IL-6 was evaluated in EV71-infected human acute monocytic leukemia cells (THP-1), differentiated macrophages derived from THP-1 cells (macrophages), and human PBMCs cells." (PMID 28854257, 2017).
Granuloma (2 papers, 2020 to 2024). A compact, organized collection of mature mononuclear phagocytes, which may be but is not necessarily accompanied by accessory features such as necrosis. "Interestingly, G-CSF/CSF-3 levels were also significantly higher in LZD+IL-1Rn treated granulomas (p = 0.0004)." (PMID 32477361, 2020).
malignant glioma (2 papers, 2023 to 2024). A grade III or grade IV glioma arising from the central nervous system. "In fact, we demonstrate that oHSV infection can induce CSF3-mediated NETosis and promote tumor survival in malignant glioma, suggesting that the effect of NETs on oHSV resistance is independent on the regulation of antitumor immunity." (PMID 38167409, 2024).
pneumococcal pneumonia (2 papers, 2020 to 2022). A febrile disease caused by STREPTOCOCCUS PNEUMONIAE. "Additionally, it would be useful to determine which subset of pulmonary cells are expressing Cxcl1, Cxcl2 and Csf3, as this may yield a focused therapeutic target to improve health outcomes in alcohol consumers with pneumococcal pneumonia." (PMID 35603143, 2022).
airway hyperresponsiveness (1 paper, 2025). "Surprisingly, the lung resistance in LPS+ OVA group of Padi4-/- mice was significantly higher than that of Csf3-/-mice, suggesting that, beyond NETs, additional neutrophil functions may contribute to airway hyperresponsiveness." (PMID 40963601, 2025).
autism (1 paper, 2020). Persistent deficits in social interaction and communication and interaction as well as a markedly restricted repertoire of activity and interest as well as repetitive patterns of behavior. "In addition, PI3K-Akt signal pathway and RAS-MAPK signal pathway are clearly related to autism, and the abnormal expression of gene CSF3 and FIGF may cause the abnormal expression of these signal pathways." (PMID 32273901, 2020). "This suggests that CSF3 is related to autism through the immune system." (PMID 32273901, 2020). "This suggests that CSF3 may influence the mechanism of autism through the immune system." (PMID 32273901, 2020). "In addition, FIGF and CSF3 may play an important role in the mechanism of autism." (PMID 32273901, 2020).
esophageal tumor (1 paper, 2021). "Upregulation of CCL20 and CSF-3 (G-CSF) has been shown in F. nucleatum-infected esophageal tumor tissue and gingival fibroblasts, respectively." (PMID 34700376, 2021).
neurofibroma (1 paper, 2021). An intraneural or extraneural neoplasm arising from nerve tissues and neural sheaths. "We have identified potential endothelial cells markers (e.g. SERPINE1, EGFL7, CSF3) based on their low expression in other non-endothelial neurofibroma cells." (PMID 33413690, 2021).
tumor (1,069 papers, 1992 to 2026). "Neutrophils increase the expression of BV8 (prokineticin-2) via CSF3, which causes myeloid cell mobility and myeloid-dependent tumor angiogenesis." (PMID 36419156, 2022). "CSF3 signaling is also associated with many of the tumor infiltrating immune populations, including T cells and macrophages, which are important regulators of the TME." (PMID 33606788, 2021). "We found critical tumor-associated T cell populations and phenotypes were associated with CSF3 signaling." (PMID 33606788, 2021). "Several tumor-derived factors, among which CSF3, IL-1β, and IL-6, have been implicated in recruitment, activation, and expansion of MDSCs." (PMID 29675018, 2018). "Our findings are supported by previous studies, indicating that CSF3 expression, and consequently the production of G-CSF, is associated not only with tumor progression but also with chemoresistance in NSCLC patients treated with the Car plus Pac doublet regimen." (PMID 39727962, 2024). "CAFs produce angiogenesis regulators, such as VEGFA, PDGFC, FGF2, CXCL12, osteopontin, and CSF3 to promote the growth of tumor-associated blood vessels by recruiting myeloid cells and accelerate tumor angiogenesis by attracting vascular endothelial cells and recruiting monocytes." (PMID 37784082, 2023). "Signalling and chronic-tumour dependent hematopoietic stimulation through the release of CSF-2, CSF-3, IL-6, and other cytokines are associated with the activation of STAT3 signalling and expression of c/EBPβ transcription factor which sustain MDSC expansion and immune suppressive features." (PMID 36161514, 2023). "We hypothesized that CSF3 signaling would correlate with pro-tumor tumor microenvironment changes associated with immune infiltrate and response." (PMID 33606788, 2021). "Moreover, increased GCSF (CSF3) expression associated with tumour grade, mutational status, immune infiltration patterns and the concomitant presence of anomalies in the JAK/STAT signaling pathway responsible for the favorable tumor microenvironment were reported." (PMID 38538691, 2024). "The results displayed that growth rates and tumor weights of xenograft tumors in the sh-NC + CSF3 group were higher than in the control group, while the knockdown of PGM2L1 abolished this trend." (PMID 40185722, 2025). "Previous studies have reported that the pro-tumor effects of CSF3 are primarily mediated by neutrophils and myeloid-derived suppressor cells(MDSCs), which are the main populations expressing CSF3R." (PMID 40185722, 2025). "It was found that CAFs upregulated the PGM2L1 in TNBC cells by secreting CSF3 under hypoxia, and then the enhanced glycolysis in tumor cells promoted progression and adapted to the hypoxic microenvironment." (PMID 40185722, 2025). "Taken together, our data verified that CAF-derived CSF3 plays a crucial role in regulating tumor growth and metastasis through PGM2L1 in TNBC." (PMID 40185722, 2025). "The MDSCs can be recruited by CSF3 secreted by tumor cells under hypoxic conditions and participate in the formation of pre-metastatic niches in the lungs." (PMID 40185722, 2025). "A similar finding was also reported in a recent study,[52b] showing that glutamine antagonism reduces MDSCs by increasing cell death and inhibiting tumor CSF3 secretion." (PMID 39482885, 2025). "Our data demonstrate that I-DXd selectively eliminates pro-tumor VEGFA+ TANs with high CSF3 expression within the TME, mitigating the potential counterproductive effects of G-CSF and enhancing the immunomodulatory impact of ADC therapy." (PMID 39971940, 2025). "Currently, it is established that CSF3 promotes growth, metastasis, angiogenesis, and modulates anti-tumor immunity in various solid tumors." (PMID 40185722, 2025). "Treatment of tumor stromal organoids in culture with docetaxel induces cytokine secretion (Csf3, Csf2, Il-6, Cxcl1, Cxcl2, and Tnfα) into the cell culture media while reducing levels of Vegf." (PMID 39338937, 2024).
tumor (continued). "Supporting this recruitment, CSF-3 and IL-17 are involved in facilitating the migration and proliferation of neutrophils, contributing to their presence at the tumor site." (PMID 38361931, 2024). "Similar analyses of Csf3 protein and mRNA expression revealed similar differences between wild-type and tumor-bearing mice after infection with MHV68." (PMID 39338937, 2024). "In multiple tumor models, tumor promotion by IL-17, IL-6, and CSF3 depends, at least in part, upon accumulation of MDSCs." (PMID 39338937, 2024). "Since the cytokines (Cxcl1 and Csf3) involved in immune cell recruitment and survival and Cd84 are elevated at day 7 in tumor-bearing mice, we tested if Ly6G+ mononuclear cells are present in MHV68-infected mice and are also a source of IL-6." (PMID 39338937, 2024). "While during PDAC progression, tumor-produced CSF3 down-regulated interferon regulatory factor-8 (IRF8) in cDC progenitors, leading to slower cDC1 development and reduced numbers." (PMID 38167055, 2024). "Corresponding to the observations here, conversion of slowly cycling tumor cells in culture to a highly proliferative and invasive phenotype requires the stromal synthesis of both CSF3 and IL-6." (PMID 39338937, 2024). "In tumor-bearing mice, the combination of CSF3 and IL-6 cooperates to convert neutrophil precursors in the bone marrow into a pro-tumorigenic phenotype, while bone-marrow-derived neutrophils from mice lacking tumors have an anti-tumorigenic effect." (PMID 39338937, 2024). "The induction of IL-6 and CSF3 in MHV68-infected K-RasLA1 mice implicates tumor promotion mediated by MDSC recruitment." (PMID 39338937, 2024). "Meanwhile, CSF cytology showed an increase in tumor cells (CSF3), so the recurrence of meningeal metastasis was considered." (PMID 37131253, 2023). "The CSF3 pathway was enriched in the DTX-treated tumor tissue defined by fibrocytes interacting with neutrophils and M2 macrophages while this phenomenon was absent in the dormant state (VEH treated)." (PMID 37699010, 2023). "An interesting report showed that metastatic tumours often overexpressed CSF-3, leading to the expansion and mobilisation of Ly6G+Ly6C+ granulocytes, which in turn produced Bv8, a protein implicated in angiogenesis and mobilisation of myeloid cells." (PMID 36161514, 2023). "Neutrophils have been suggested to facilitate tumor growth and malignancy, as evidenced by research indicating that Csf3-/- neutropenic mice present a modest tumor growth delay in an LLC1 tumor model and diminished urethane-induced lung carcinogenesis." (PMID 36514901, 2022). "CSF3 also correlated strongly with WNT5a expression, which can promote or inhibit tumor growth dependent on its isoform." (PMID 33606788, 2021). "CSF3 inhibition increased T cell infiltration, and decreased neoplasm development by 75% in the AOM/DSS model of CRC development." (PMID 33606788, 2021). "In CC, we see shifts in multiple T cell phenotypes, both towards pro-tumor and anti-tumor responses that correlate with CSF3 and CSF3R expression." (PMID 33606788, 2021). "Identification of these often-intertwined pathways suggests a relationship between CSF3 signaling and cell proliferation and tumor progression." (PMID 33606788, 2021). "This was true for established gene signatures, like the ESTIMATE scores, but we also observed many of the same genes significantly correlated with CSF3/R expression in both tumor types." (PMID 33606788, 2021). "The Cancer Genome Atlas (TCGA) data analysis revealed that CSF3 and CSF3R are associated with a large number of changes in the tumor microenvironment of CRC." (PMID 33606788, 2021). "Here, we show that expression of CSF3 and CSF3R are associated with CMS1 and CMS4 classifications, pro-tumor gene scores, and regulation of both innate and adaptive cells in the TME." (PMID 33606788, 2021). "CSF3 increases tumor cell proliferation, migration, and the proportion of stem-like cells in culture in CRC." (PMID 33606788, 2021).
tumor (continued). "For certain genes (Il10, Csf3, Cxcl1, Ccl2, Gata3, Il5, and Il13), there was a clear difference between the EC and HC Shb KO effects using Cdh5-CreERt2 or Vav1-Cre tumor-bearing mice, indicating that these effects reflect EC cell autonomy of Shb gene deletion." (PMID 34768912, 2021). "We have identified granulocyte colony-stimulating factor (G-CSF, also known as CSF3) as a tumor promoting cytokine that is produced by epithelial cells, monocytes/macrophages, fibroblasts and bone marrow stromal cells." (PMID 33042110, 2020). "Several studies also identify tumor-derived CSF3 (also known as G-CSF) as a cytokine that recruits myeloid cells to the TME, and CSF3 is associated with T cell inhibition and desensitization of PDAC tumors to immunotherapy." (PMID 33304355, 2020). "With respect to patient age at diagnosis, LUAD patients who were diagnosed >65 years old showed a shorter RFS when their tumor expressed a high level of CSF3 (HR = 1.666, 95% CI = 1.09–2.547, and p = 0.0184 for the high vs. low CSF3 expression >65 subgroup)." (PMID 31004093, 2019). "Tumor -produced CSF3, IL-1β, and IL-6 activate STAT3 in MDSCs which leads to their expansion but hinders MDSC maturation into macrophages or neutrophils." (PMID 31572387, 2019). "In another independent cohort (BELOB trial), which compared lomustine versus lomustine plus bevacizumab at recurrence, bevacizumab only benefited patients with high CSF3 expression in the tumor." (PMID 27487142, 2016). "Together, these data demonstrate that tumor CSF3 expression, like the neutrophil count, can predict bevacizumab efficacy." (PMID 27487142, 2016). "Mutations that no longer require or are hyperresponsive to CSF3 result in the overproduction of neutrophils and their precursors with additional cooperating mutations leading to neoplasia." (PMID 41154433, 2025). "The chemokines CSF-1 (also known as M-CSF), CSF-2 (also known as GM-CSF), and CSF-3 (also known as G-CSF) are also shown to be expressed by PCCs, leading to decreased concentrations of anti-tumor dendritic cells and increased concentrations of immune suppressive cells within the TME." (PMID 38361931, 2024). "However, future experiments will be required to verify that CSF3 and IL-6 are involved in tumor promotion in this model." (PMID 39338937, 2024). "CSF cytology revealed a large number of tumour cells (CSF3)." (PMID 37897649, 2023). "A significant positive association occurred between five types of immune cells and CSF3 expression (r > 0.30, p < 0.05), including cytotoxic T cells, Th17 cells, neutrophils, and DC cells, all immune cells having a favorable correlation with PDCD1 and CSF3 showed anti-tumor properties." (PMID 37644514, 2023). "CSF3 is a pleiotropic cytokine that has significant effects on tumor and immune cells." (PMID 33606788, 2021). "Tumor-derived factors, such as G-CSF (also known as CSF3), GM-CSF (also known as CSF2), and IL-6 drive this myeloid bias and increase the circulating and tumor-infiltrating MDSC population, which accelerates tumor progression by suppressing T cell responses and releasing metabolic factors." (PMID 34248988, 2021). "CSF3 signaling is associated with changes in the immune infiltrate within the TME and demonstrates strong correlation with gene signatures associated with pro-tumor immune responses." (PMID 33606788, 2021). "Currently, it is unknown whether CSF3 and CSF3R expression are associated with patient demographics, stage at presentation, location of tumor, mutational status, CMS subtype, or distinct patterns of immune infiltrates." (PMID 33606788, 2021). "We hypothesized that CSF3 and CSF3R would be associated with pro-tumor immune signatures and pathways." (PMID 33606788, 2021).
tumor (continued). "The expression levels of these cytokines were assessed in 4T1 tumours, which revealed a striking similarity to the reparative tissue response, including significantly higher Spp1, Il1b, Csf3, Il6 and Osm expression in 4T1 tumours compared to healthy mammary fat pad tissue." (PMID 30054470, 2018). "Furthermore, treatment with neutralising anti-CSF-1R or anti-CSF1 antibodies can lead to a compensatory increase in granulocyte colony stimulating factor (CSF3), which stimulates an increase in neutrophils at the primary tumour site and in metastatic deposits." (PMID 28210073, 2017). "Importantly, in a series of 12 GBM, CSF3 (the gene coding for G-CSF) expression in the tumor bed correlated strongly with the neutrophil count (r2 = 0.36; p = 0.04)." (PMID 27487142, 2016). "For instance, CSF3 (colony stimulating factor 3), also known as G-CSF, produced by tumor cells can lead to the differentiation of CD11b+Gr1+ myeloid cells into neutrophils, macrophages, and dendritic cells, that have been shown to be overproduced in cancer patients and tumor-bearing mice." (PMID 23372791, 2013). "Cxcl2, Ccl2, Ccl3, and Ccl8 can act as chemoattractants for myeloid cell recruitment in tumors, while Csf1, Csf2, and Csf3 are central to controlling the recruitment, proliferation, and differentiation of immunosuppressive myeloid cells, including macrophages and neutrophils in the tumor." (PMID 37138326, 2023). "In other studies, the inhibition of tumor glutamine metabolism could decrease the recruitment and infiltration of MDSCs by increasing cell death and decreasing tumor CSF3 expression, and this led to an increase in inflammatory TAM differentiation and inhibited tumor growth." (PMID 34638609, 2021). "We identified six cell types, including macrophages (PPP1R17), monocytes and neutrophils (FCAR, S100A12, CD93), tumor stem cells (CPZ), smooth muscle cell populations and epithelial cells (CSF3, TTC23L)." (PMID 41049004, 2025). "Across multiple preclinical tumor models, RT has been shown to increase the expression of cytokines such as IL-1β, GM-CSF (CSF2), and G-CSF (CSF3), along with chemokines including CXCL1, CXCL2, CXCL5, CCL2, and CCL5." (PMID 40805288, 2025). "Upon tumor cell activation, a large number of CXCL5, CXCL3, CSF3, CCL20, and CXCL1 are expressed to recruit neutrophils." (PMID 38167055, 2024). "Collectively, these findings provide strong evidence that the effects of BET inhibitors on NETosis and tumor survival inhibition result, in part, from the downregulation of IGF2BP3 and subsequent decrease in CSF3 expression." (PMID 38167409, 2024). "Since the literature has demonstrated that IL-17, IL-6, and CSF3 promote lung tumorigenesis, we conjecture that MHV68 induces tumor promotion via induction of these cytokines." (PMID 39338937, 2024). "In both analyses, all genes except CSF3 and FST were differentially expressed between the tumour and tumour-adjacent tissue." (PMID 37509322, 2023). "In a group of patients with stages IB–IV EC (n = 11), TIMP2, CSF3, ENPP2, and SERPINF1 were significantly down-regulated in tumour tissue, by 4.9-fold, 9.6-fold, 10.2-fold, and 9.2-fold, respectively." (PMID 37509322, 2023). "To further investigate changes in the tumor microenvironment, we determined the levels of TAM‐produced cyto/chemokines Ccl2, Ifnγ, Cxcl10, Cxcl9, Csf1, Csf3, and Il‐6 in the peritoneal lavage." (PMID 36221913, 2022). "We examined correlations of CSF3 and CSF3R expression with patient demographics, tumor stage and consensus molecular subtype classification." (PMID 33606788, 2021). "To directly test if tumor-derived GCSF was responsible for impaired cDC development, we deleted the Csf3 gene using CRISPR CAS9 in the PyMT-B6 cell line (PyMT-B6 GCSFKO)." (PMID 29593283, 2018). "First we analyzed both tumor tissues and BM samples from the transplantable PyMT-B6 and the genetic KPC models for Csf3 by in situ hybridization (ISH)." (PMID 29593283, 2018).